RN7SKP177 (RN7SK pseudogene 177)
Gene: Miscellaneous RNA gene on chromosome 3 (157,017,342 to 157,017,696, forward strand). Ensembl gene ENSG00000222499.
Homologues: Orthologues: guinea pig 7SK (42% identical), mouse Gm54764 (39% identical). Paralogues in human: RN7SKP79 (67% identical), RN7SKP240 (65% identical), RN7SKP71 (65% identical), RN7SKP294 (65% identical), RN7SKP90 (64% identical), 7SK (64% identical), RN7SKP255 (64% identical), RN7SKP77 (64% identical), RN7SKP124 (63% identical), RN7SKP180 (63% identical), RN7SKP47 (63% identical), RN7SKP1 (62% identical), and 284 more.